CRP (C-reactive protein)
Diseases named in the same sentence as CRP in open-access papers (continued):
Sharing a sentence is not in itself a finding about the gene and the disease.
Obesity (continued). "Moreover, Hs-CRP level was higher in both patients with HFpEF and obesity and patients with obesity versus controls." (PMID 36386034, 2023). "Obesity induces persisting low-grade inflammation because of increasing macrophage infiltration, which further activates immune cells to release proinflammatory cytokines (i.e., CRP, TNF-α, and IL-6) into the circulation." (PMID 37778442, 2023). "IL-6 induces hepatocytes to produce and release inflammatory molecules, c-reactive protein (CRP) that indicates liver-caused systemic inflammation which controls obesity regardless of race and gender." (PMID 37229273, 2023). "CRP followed the same pattern as obesity measures, with significant inverse correlations for 3/70 markers, whereas insulin levels at the end of the hyperinsulinemic-euglycemic phase displayed positive weak tendencies with inflammatory responses (Supplement S3)." (PMID 37400734, 2023). "As a marker of low-grade inflammation, the hs-CRP level is chronically elevated in people with obesity, which may explain the positive correlation." (PMID 36797524, 2023). "A meta-analysis has shown that obesity can alter serum levels of pro-inflammatory mediators (i.e., IL-6, CRP, TNF-a, resistin and leptin) in patients with periodontitis, while periodontitis can alter the levels of these mediators in patients with obesity, aggravating the inflammatory profile." (PMID 37798684, 2023). "One hypothesis to explain these discrepancies is possible confounders, such as smoking, obesity, and compliance, which may contribute to high CRP levels despite antihypertensive drug therapy." (PMID 38098917, 2023). "Vitamin D supplementation may decrease blood CRP levels in children with overweight and obesity and improve inflammatory markers in pediatric intestinal bowel syndrome." (PMID 37603433, 2023). "At the same time, zinc demonstrated potential anti-inflammatory effects through cytokine signaling pathways and the reduction of plasma levels of IL-6, TNF-α, and CRP, with a protective effect against chronic low-grade inflammation, which is found in obesity and MetS." (PMID 38140353, 2023). "In other words, obesity with elevated CRP poses a risk for cardiovascular events that again show increased CRP values; therefore, it does not seem to be CRP, but rather obesity itself." (PMID 37873776, 2023). "The objectives of this study were to examine the effect of obesity on the relationship between peripheral and gingival CRP levels and to examine the effects of gingival CRP levels on gingival fluid inflammatory cytokines in periodontitis-resistant obese individuals." (PMID 38138192, 2023). "Additionally, we validated that the association between obesity-related DP and overall cancer was mainly mediated by the BMI and WHR (two response variables) and along with C-reactive protein and HDL and triglycerides." (PMID 37424008, 2023). "CRP levels can also be influenced by other factors such as obesity, physical activity and diet, which may confound signals between CRP and CVD still further." (PMID 37498390, 2023). "In addition, 3 months of low-volume high-intensity interval cycling (80%–95% HRmax, 2 sessions/week) meaningfully reduced CRP and IL-6 while increasing VO2max in metabolic syndrome patients (mean age 53.7 years) with obesity." (PMID 37608837, 2023). "Yet, the SEM analyses showed no significant direct or indirect association of obesity with ID but showed an indirect pathway/association via CRP." (PMID 36996088, 2023). "Altogether, these findings suggest that systemic low-grade inflammation may act as a potential mediator of the relationship between obesity and PC, and the common marker of systemic inflammation includes CRP." (PMID 36816931, 2023). "However, for geriatric subjects, the most important factors were obesity, albumin, total bilirubin, alanine aminotransferase, serum ferritin, C-reactive protein and LDH." (PMID 36899318, 2023).
Obesity (continued). "The next step might be to consider a larger sample size for combined periodontal and obesity treatment, as well as a longer suitable observation time to monitor CRP levels and periodontitis." (PMID 37481511, 2023). "In detail, a low-grade elevation of CRP is associated with a wide range of chronic conditions resulting in metabolic stress (e.g., obesity, atherosclerosis, obstructive sleep apnea) and not with acute infection." (PMID 36673130, 2023). "Elevated levels of CRP are linked to metabolic syndrome, T2D, CVD and obesity." (PMID 36771387, 2023). "Serum CRP levels were higher among children with overweight/obesity with MetS." (PMID 36920931, 2023). "(2005), metabolic syndrome in women who participated in the British women’s heart and health study was associated with obesity rather than CRP haplotype." (PMID 37520541, 2023). "CRP is elevated in many inflammatory conditions, including obesity." (PMID 38138192, 2023). "Obesity-related leptin resistance mechanisms and inflammatory factors (including tumor necrosis factor-α, interleukin-1β, and C-reactive protein) mediate inflammatory responses suppress hypothalamic-pituitary-gonadal axis function in obese men, leading to decreased body testosterone levels." (PMID 37361537, 2023). "This current systematic review and meta-analysis investigated the effect of dietary ALA on CVD risk factors, including inflammatory markers (CRP, IL-6, and TNF-α in serum), BP, and blood lipid profile (TG, TC, LDL cholesterol, and HDL cholesterol in serum) in patients with overweight or obesity." (PMID 37778442, 2023). "Although the increase in CRP and plasma leptin concentration has been observed in obesity, it is unclear whether elevation in CRP is due to acute inflammation, adipose tissue expansion, or both." (PMID 36771307, 2023). "Obesity predisposes to a low-grade pro-inflammatory state via increased inflammatory mediators IL-6 and TNF-α, which in turn triggers hepatocyte expression and release of serum high-sensitive C-reactive protein (hs-CRP)." (PMID 37504556, 2023). "Thus, the current study was only able to use hs-CRP and omega-3 data to investigate inflammation in obesity." (PMID 37754594, 2023). "Obesity causes mild inflammation and can hasten the development of chronic diseases and their complications by secreting pro-inflammatory cytokines such as interleukin-6 (IL-6), tumor necrosis factor (TNF), and C-reactive protein (CRP)." (PMID 37275644, 2023). "Moreover, a cross-sectional study among Iranian women with obesity also shown that higher hPBD adherence was related to lower transforming growth factor and CRP levels." (PMID 37193979, 2023). "We had already demonstrated in a previous uncontrolled, single - center, open - label pilot clinical study in 260 women with overweight or obesity that hs - CRP levels decreased (∆-38.9 ± 45.6%) while PhA increased (∆+8.6 ± 12.5%) after 31 days of an active phase of VLCKD." (PMID 36800966, 2023). "A high CRP concentration in an obese SLE patient linearly increases the risk of CVD, and CRP is an independent predictor of SLE, possibly attributed to its pro-inflammatory effect in obesity." (PMID 36839394, 2023). "Healthy lifestyle, including leisure time physical activity, healthy diet, and weight loss can improve energy balance and may reduce obesity-related inflammation, such as IL-6, TNF-α, and CRP." (PMID 37764780, 2023). "We focused on postoperative serum CRP level according to the combination of obesity and PAIC." (PMID 37344511, 2023). "Semaglutide is another GLP-1RA that has also gained interest in the treatment of steatohepatitis, as several studies in patients with T2DM and obesity reported beneficial changes in liver enzymes and inflammatory biomarkers such as high-sensitivity C-reactive protein." (PMID 37233622, 2023).
Obesity (continued). "In this cross-sectional study of children and adolescents with obesity, we found an inverse association between cardiorespiratory fitness and hs-CRP, that was independent of BMI SDS." (PMID 37147377, 2023). "Obesity is a proinflammatory state and circulating C-reactive protein is elevated in obesity." (PMID 35757166, 2022). "•23% of the obesity effect on PF operated via a downstream effect on CRP." (PMID 35301057, 2022). "In conclusion, the results of this retrospective case study performed in a Mexican population indicates that metabolic disorders such as: obesity, T2DM, and hypertension, as well as elevated levels glucose, IL-6, LDH and CRP are associated with the SARS-CoV-2 infection severity." (PMID 35464048, 2022). "In obesity, accumulation of free fatty acids activates pro-inflammatory serine kinase cascades, which in turn promotes adipose tissue to release interleukin-6 that stimulates hepatocytes to synthesize and secrete CRP." (PMID 36235852, 2022). "Due to the clinical features of obesity and abdominal obesity, it may have higher levels of inflammatory cytokines and adipokines (eg, interleukin-1, interleukin-6, C-reactive protein, tumor necrosis factor alpha)." (PMID 35846319, 2022). "In addition, the serum levels of CRP were statistically higher in patients with obesity versus patients with normal weight (p = 0.0004)." (PMID 36558394, 2022). "The study reported a high prevalence of physical inactivity, high CRP, and overweight/obesity in the sampled population, and these factors may have diminished the protective role of PA in the relationship between CIMT and obesity." (PMID 35627885, 2022). "Obesity is associated with chronic inflammation, which is characterized by increased levels of several pro‐inflammatory cytokines, including interleukin 6 (IL‐6), tumor necrosis factor‐α (TNF‐α) and C‐reactive protein (CRP)." (PMID 35293040, 2022). "CRP is a pentameric protein with hepatic origin related to inflammation process and obesity." (PMID 35679338, 2022). "CRP is often higher in patients with obesity as compared to normal‐weight controls and is associated with the low‐grade inflammation characteristic of obesity." (PMID 35837843, 2022). "Interestingly we found increased levels of systemic inflammation markers (CRP and lymphocytes) among metabolically healthy preadolescents with overweight and obesity in comparison to healthy participants, in line with previous studies." (PMID 36498548, 2022). "In particular, hydroxylated VLCFA-variant GM3 h24:0 was strongly positively correlated with body mass index (BMI; marker of obesity), abdominal circumference, and C-reactive protein (CRP; marker of chronic inflammation and surrogate marker for inflammatory cytokine IL-6) level." (PMID 35712350, 2022). "That finding is consistent with the finding that inflammation is an important risk factor for lung cancer and that vitamin D does not reduce the raised CRP associated with obesity." (PMID 36145186, 2022). "Stratified analyses revealed a significant association between the obesity phenotypes and decreased eGFR in non-smokers, non-drinkers, hs-CRP > 0.01 mg/dL, and both physical activity groups." (PMID 36142036, 2022). "A recent review study has reported that Mediterranean diets, which are rich in fish, fruits, vegetables and, olive oil, may decrease inflammatory factors such as CRP, IL-6, and fibrinogen as well as risks of obesity." (PMID 35501761, 2022). "Unhealthy lifestyle, e.g., obesity, smoking, and alcohol consumption increase concentrations of inflammatory markers, of which especially CRP, TNF-α and IL-6 may contribute to the development of insulin resistance and cardiometabolic diseases." (PMID 35831939, 2022).
Obesity (continued). "In humans, increased circulating MCP-1 correlates with higher levels of other inflammatory markers such as C-reactive protein (CRP) and interleukin-6 (IL-6), but also obesity, waist circumference, and the homeostatic model assessment for insulin resistance (HOMA-IR) score." (PMID 36106024, 2022). "For example, the TE of overweight/obesity on poor PF, expressed as an OR, was 1.66 (95% CI: 1.37, 2.01), with a direct effect of 1.46 (1.19, 1.78); the proportion of the total effect mediated by CRP was 26.12% (95% CI: 2.40, 49.84)." (PMID 35301057, 2022). "In obesity, excess adipose tissue—in particular, visceral adipose tissue—releases proinflammatory cytokines and CRP, which then stimulate the production and release of APPs from hepatocytes, macrophages, and others, creating an environment of prolonged, low-grade, systemic inflammation." (PMID 36475018, 2022). "Children and adolescents with obesity had higher concentration of 25(OH)D3 and CRP than Children and adolescents with different nutritional conditions had different vitamin A status (c2 = 12.704, p = 0.048), while their vitamin D status was similar (c2 = 15.443, p = 0.079)." (PMID 35379317, 2022). "ISARIC-4C is based on the components of the Charlson Index and CURB-65, along with gender, obesity and CRP to build a model with 8 predictor variables, including 2 biochemical which limits its application outside the hospital context; unexpectedly, hypotension has not reached the final model." (PMID 35149742, 2022). "Obesity is connected with inflammation, evidenced by increased C-Reactive protein (CRP) levels." (PMID 36299943, 2022). "Obesity also raises CRP, so patients should be advised to reduce their weight." (PMID 35965526, 2022). "We found that CRP and the TyG index mediated the association of obesity, assessed by WC rather than BMI, with CRC risk." (PMID 36407320, 2022). "It is known that pre-pregnancy obesity and several lifestyle factors, including a diet rich in meat and processed foods, correlate directly with circulating concentrations of inflammatory biomarkers, such as CRP and IL-6." (PMID 35270396, 2022). "Though CRP is a surrogate of systemic inflammation, the biological substrate that links aging with obesity might be the systemic inflammation itself." (PMID 36012914, 2022). "In univariate analysis, we found that the duration of hospitalization is influenced by: the duration of symptoms before the consultation, obesity, presence of dyspnea at admission, CRP value at admission higher than 300 (mg/l), A lymphocyte count on admission of less than 1000/μl." (PMID 35784951, 2022). "BMI and expression levels of serum inflammatory markers, namely, hypersensitive C-reactive protein, procalcitonin, and interleukin-6, were found to be significantly positively correlated, and obesity may increase the correlation between PCOS and inflammation." (PMID 35547654, 2022). "We searched PubMed on 28 June 2021 for articles published in the past 5 years, with no language restrictions, using the search terms “cardiometabolic”, “cardiovascular”, “C-reactive protein”, “inflamm∗”, “glucagon-like peptide-1 receptor agonist”, “obesity”, and “overweight”." (PMID 36467859, 2022). "In the current study, participants with a BMI in the normal range (≤25) were recruited to avoid any obesity-induced increases in basal CRP levels, which may have added a confounding element to the study results." (PMID 35277071, 2022). "The higher CRP prevalence (41%) may be explained by the high prevalence of overweight and obesity in our study population, as CRP (an inflammatory marker) is often increased in persons with increased central obesity." (PMID 35627885, 2022). "The Women’s Health Study and Physicians’ Health Study both demonstrated that the circulating level of CRP is a predictor of future cardiovascular events, independent of other risk factors including hypertension, obesity and hypercholesterolemia." (PMID 36177015, 2022).
Obesity (continued). "Interestingly, in a Brazilian longitudinal study of adult health, obesity was considered as one of the most important confounders in the association study between TSH and CRP." (PMID 35996695, 2022). "Median CRP levels were higher in our patients when compared to reference values (0.25 vs. <0.05 mg/dL, respectively; p < 0.01), consistent with previous findings correlating obesity with inflammation also in our cohort." (PMID 36079892, 2022). "Additionally, the Coronary Artery Risk Development in Young Adults (CARDIA) study indicated that Mg intake is inversely related to the incidence of obesity and C reactive protein levels." (PMID 36235758, 2022). "In addition, due to the clear link between obesity and cataract caused by chronic inflammation and inflammatory markers such as CRP, IL-6 and TNF-α, and urinary isoprostanes, it is apparent that obesity is a risk factor contributing to cataract." (PMID 35565652, 2022). "Therefore, the aim of the present study was to perform a systematic review of the relationship between PD and obesity based on the values of the inflammation markers IL-6 and CRP detected in previously studied individuals." (PMID 36547041, 2022). "Elevated levels of IL-6, Interleukin-8 (IL-8), TNF-α, C-Reactive Protein (CRP), leptin, and a lower level of adiponectin may represent the pathogenetic link between obesity-induced hypoxemia and respiratory disorders." (PMID 36143014, 2022). "The AT, RT, and AT + RT all improved BMI in adolescents with obesity while reducing levels of the inflammatory response factor CRP; AT + RT was more effective than other training modalities in reducing the inflammatory response factor CRP in adolescents with obesity." (PMID 36293806, 2022). "Importantly, we provide novel findings regarding the potential mediating role of inflammation on the obesity-poor PF relationship, showing that approximately 23% of the obesity effect operates via a downstream effect on CRP." (PMID 35301057, 2022). "However, its accuracy is low within the first 48 h of symptom onset, and as CRP is synthesized in the liver from serum cytokine actions, it can be underestimated in patients with liver disease due to alcoholism or obesity, which is common in AP." (PMID 35744050, 2022). "Obesity is associated with chronic low-grade systemic inflammation (metabolic inflammation) as witnessed by increased blood concentration of TNF-α, C-reactive protein (CRP) and IL-1β." (PMID 35335211, 2022). "In addition to central adiposity, generalized overweight and obesity are accompanied by chronic inflammation reflected in higher CRP levels." (PMID 35035976, 2022). "Nonetheless, our mediation analysis relies on several assumptions including no confounding of the obesity-poor PF, obesity–CRP and CRP–poor PF associations." (PMID 35301057, 2022). "The functional framework between IL-6 and CRP may be strongly influenced by the increased production of IL-6 by human adipose tissue in cases of obesity." (PMID 34813039, 2022). "Obesity must be perceived as the situation of permanent low-grade inflammation with activation of various signaling pathways in its course mediated via, e.g., CRP and NF-κB." (PMID 36235636, 2022). "Broadly similar patterns of associations were observed when, (i) the exposure was overweight/obesity at 33y, (ii) we included individuals with CRP > 10 mg/l (n = 179) in the analysis and (iii) we considered waist-hip ratio at 45y as an additional intermediary confounder." (PMID 35301057, 2022). "CRP levels of >1.0 mg/L were evident among children with obesity as early as 3 years old." (PMID 36292751, 2022). "Consistently, we demonstrated that patients with MAFLD had significantly higher BMI, WC, ALT, AST, γ-GT, TG, FINS, HOMA-IR, and CRP levels as well as increased proportions of obesity, hypertension, hyperlipidemia, IR, hepatic steatosis, and fibrosis compared with those without MAFLD in both genders." (PMID 35222274, 2022).